MIR665 (microRNA 665)
Synonyms: hsa-mir-665; MIRN665; mir-665
Gene: MicroRNA gene on chromosome 14 (100,875,033 to 100,875,104, forward strand). Ensembl gene ENSG00000283159.
Gene Ontology:
Biological process: miRNA-mediated post-transcriptional gene silencing
Cellular component: RISC complex
Homologues: Orthologues: chimpanzee ptr-mir-665 (97% identical), mouse Mir665 (89% identical), rat Mir665 (89% identical).